H2AX (H2A.X variant histone)
Diseases named in the same sentence as H2AX in open-access papers (continued):
Sharing a sentence is not in itself a finding about the gene and the disease.
B cell lymphomas (7 papers, 2012 to 2023). "In B‐cell lymphoma, NCL KD sensitized cells to FasL‐induced apoptosis and induced phosphorylation of H2AX and B‐cell lymphoma survival." (PMID 31127617, 2019). "The ability of H2AX to suppress translocations has also been demonstrated in experiments with Eμ-c-Myc transgenic mice where a decrease in H2AX gene copy number lead to unbalanced clonal and non-clonal translocations in B cell lymphomas of Eμ-c-Myc+/− mice." (PMID 28914798, 2017). "In order to verify this hypothesis we investigated the expression of the phosphorylated form of the histone H2AX at serine 139 (γH2AX), a marker of DDR activation and DNA double strand breaks, in our B-cell lymphoma panel." (PMID 25544753, 2015).
breast tumor (7 papers, 2010 to 2020). "(b) Breast tumors from MDA-MB-231 cells treated or untreated with SMIP004 or radiation were harvested from nude mice at 6 week for γ-H2AX staining by IHC and quantitated (Scale bars, 50 um, Scale bars inside the box, 20 um)." (PMID 30760284, 2019). "(a) Breast tumors from MCF-7 cells treated or untreated with SMIP004 or radiation were harvested from nude mice at 6 week for γ-H2AX staining by IHC and quantitated (Scale bars, 50 um, Scale bars inside the box, 20 um)." (PMID 30760284, 2019). "The expression of both the H2AX gene and miR-24-2 in individual patients with tumors at different stages was again observed to have an inverse relation, confirming miR-24-2 as a strong regulator of H2AX in in vivo sporadic breast tumors." (PMID 21463514, 2011). "It was observed that H2AX gene expression was negatively correlated with miR-24-2 expression and not in accordance with the gene copy number status, both in cell lines and in sporadic breast tumor tissues." (PMID 21463514, 2011). "It has been shown that triple-negative and HER2+ primary breast tumors exhibited higher frequency of expression of γH2AX, a component in the ATM/H2AX DNA damage response complex that facilitates the DNA damage repair." (PMID 30746635, 2019). "One such miR, hsa-miR-24-2, that has been reported to be a strong regulator of H2AX expression was confirmed in our study, both in cell lines and in sporadic breast tumor samples, irrespective of CNA." (PMID 21463514, 2011).
Fanconi anemia (7 papers, 2016 to 2024). Fanconi anemia (FA) is a hereditary DNA repair disorder characterized by progressive pancytopenia with bone marrow failure, variable congenital malformations and predisposition to develop hematological or solid tumors. "This pathway involves multiple proteins, including BRCA1, BRCA2, proteins of the MRN complex, CtIP, RAD51, ATM, H2AX, PALB2, RPA, RAD52, and proteins of the Fanconi anemia pathway." (PMID 38236558, 2024). "Activated ATR allowed the recruitment of the Fanconi anemia DNA cross-link repair pathway, evidenced by the activation of FANCD2 and its recruitment in subnuclear foci together with p-H2AX." (PMID 29559578, 2018).
head and neck cancer (6 papers, 2013 to 2024). A primary or metastatic malignant neoplasm affecting the head and neck. "To determine which particular events caused the phosphorylation of H2AX in HPV-positive head and neck cancer cells after roscovitine treatment, we tracked the formation of 53BP1 foci as a marker of DNA double strand breaks (DSBs)." (PMID 27233076, 2016). "In contrast, we found a significant decrease in H2AX phosphorylation in HPV-negative SCC61 head and neck cancer cells after roscovitine treatment." (PMID 27233076, 2016). "Additionally, AZD1775 in combination with the Aurora Kinase A inhibitor, alisertib, also demonstrated an enhanced anti-tumor effect with increases in apoptosis and γ-H2AX in head and neck cancers." (PMID 32204315, 2020). "Therefore, p-H2AX may also be an independent prognostic predictor of head and neck cancer and a potential therapeutic target." (PMID 39199151, 2024).
myeloma (6 papers, 2013 to 2025). "We previously reported that exposure to SAHA induced the persistence of γ-H2AX nuclear foci in irradiated multiple myeloma cells, which was associated with the inhibition of RAD51-dependent HDR." (PMID 24367670, 2013). "A3B knockdown also decreased the basal levels of γ-H2AX foci, suggesting that A3B promotes constitutive DNA double-strand breaks in myeloma cells." (PMID 31073151, 2019). "In line with this interpretation, bortezomib strongly induced γ-H2AX accumulation after 24 h of treatment in myeloma cells across six validation samples of newly diagnosed patients, notably higher than the γ-H2AX levels induced in the same samples by the DNA-damaging agent bendamustine." (PMID 37081258, 2023). "Of note, to our knowledge, there are no reports on the induction of H2AX levels by proteasome inhibitors in other disease entities, such as multiple myeloma." (PMID 32198455, 2020).
diabetes (5 papers, 2012 to 2025). "Using db/db mice as a model of obesity-induced T2D along with background-matched BKS controls, we observed a β-cell-specific increase in H2AX (both punctate and pan-nuclear) in 8-week-old db/db mice, a stage marked by hyperglycemia preceding diabetes onset." (PMID 41292712, 2025). "γ-H2AX is a marker of the formation of double-strand breaks as a response to exposure to DNA damaging factors and has been used for drug development and clinical studies on diabetes." (PMID 34961280, 2021). "Since both studies used volunteers who were likely healthier than age-matched patients in the general population, a cohort which included patients with dementia, metastatic cancer, heart disease, and diabetes may have revealed a slope of the γ-H2AX levels after age 50 with an upward trajectory." (PMID 23029205, 2012). "γ-H2AX and COL6 were examined in 25 samples (8 diabetes mellitus, 6 nephrosclerosis, and 11 transplanted allografts) and 5 samples of minimal change disease as controls." (PMID 33335142, 2020).
endometriosis (5 papers, 2018 to 2026). The growth of functional endometrial tissue in anatomic sites outside the uterine body. "Endometriosis-derived EEOs exhibited elevated baseline γH2AX (phosphorylated histone H2AX) immunofluorescence compared with controls (2.32 ± 0.44 vs. 1.00 ± 0.28, p = 0.05), indicating increased DNA double-strand break accumulation." (PMID 41977222, 2026). "Choi and colleagues have also found higher gamma H2AX in endometriosis compared to non-endometriosis but an increase in ovarian endometrioma H2AX compared to eutopic endometrium." (PMID 36674426, 2023). "Uniform and strong nuclear γ-H2AX expression was also observed in ectopic endometrium of patients with endometriosis." (PMID 30622513, 2018). "After H2O2 treatment, γ-H2AX expression levels were also significantly greater in cultured stromal cells of the endometriosis group and in the Ishikawa cell line than in controls." (PMID 30622513, 2018). "After H2O2 treatment of cultured Ishikawa cell lines and endometrial stromal cells from patients with endometriosis and controls, γ-H2AX expression as a marker of DNA DSB was measured by western blot." (PMID 30622513, 2018). "In the present study, we found that occurrences of DNA DSBs, as represented by γ-H2AX protein expression, increased in endometrial, and ovarian endometrioma samples of patients with endometriosis." (PMID 30622513, 2018). "We evaluated γ-H2AX protein expression in eutopic and ectopic endometrial tissues of patients with or without endometriosis in immunostained tissue sections." (PMID 30622513, 2018).
rectal cancer (5 papers, 2013 to 2021). A primary or metastatic malignant neoplasm that affects the rectum. "A statistically elevated number of H2AX positive epithelial cells in rectal carcinoma tissue is a biomarker for DNA damage induced by DNA double-strand breaks." (PMID 27045955, 2016). "The presence of statistically elevated expression of H2AX in mice with rectal carcinoma also provides support for the EHS, or other bacteria, in driving a carcinogenic process." (PMID 27045955, 2016). "The study shows higher expression of γ-H2AX and 53BP1 foci in rectal cancer patients compared with healthy individuals." (PMID 26541290, 2015). "The prognostic value of histone γ-H2AX and 53BP1 proteins to predict the radiotherapy (RT) outcome of patients with rectal carcinoma (RC) was evaluated in a prospective study." (PMID 26541290, 2015). "Moreover, high expression of VSTM2L reduced γ-H2AX expression in rectal cancer patient-derived organoids treated with CRT." (PMID 33506057, 2021). "Indeed, we found that AZD7762 treatment abrogated the IR-induced G2 arrest and led to increased phosphorylation of H2AX (γH2AX) and apoptosis in the rectal cancer cell lines." (PMID 24349411, 2013).
thyroid cancer (5 papers, 2013 to 2022). "PXD101 significantly induced p-H2AX in three thyroid cancer cell lines, supporting DSBs as one mechanism accounting for the cytotoxicity of PXD101." (PMID 24155971, 2013). "Our result showed canagliflozin increased γ-H2AX levels in thyroid cancer." (PMID 35148777, 2022). "p-H2AX (Ser139), a traditional DSBs marker was significantly enhanced with a dose-dependent manner in all cell lines, supporting PXD101 can induce DSBs in thyroid cancer cells." (PMID 24155971, 2013). "At present, there are only two studies that have quantified radiation-induced DNA damage focus formation after treatment of differentiated thyroid cancer (DTC) with the isotope 131I, either using radiation-induced colocalizing γ-H2AX and 53BP1 foci or γ-H2AX foci only." (PMID 26048612, 2015). "After molecular therapy (MRT) of differentiated thyroid cancer with the isotope I-131 there are only two studies that quantified DSB foci response, using either radiation-induced γ-H2AX and 53BP1 foci or only γ-H2AX foci." (PMID 25853575, 2015).
acute myeloid leukaemia (4 papers, 2017 to 2024). "The loss of H2AX increased chromosomal instability seen in acute myeloid leukemia, acute lymphoid leukemia, and Head and neck squamous cell may contribute to tumor development, progression, and resistance to therapy in this cancer subtype." (PMID 38566813, 2024). "Interestingly, H2AX appears to be upregulated in most cancers when compared to controls with the exception of acute myeloid leukaemia." (PMID 32887437, 2020).
brain tumor (4 papers, 2019 to 2025). "HPRT1 depletion inhibited TMZ treatment-induced AMPK activation in brain tumor tissues and enhanced TMZ-induced γ-H2AX levels and apoptosis." (PMID 37737247, 2023).
endometrial cancer (4 papers, 2014 to 2024). Primary or metastatic malignant neoplasm involving the endometrium (mucous membrane that lines the endometrial cavity). "To further validate the effect of the combination treatment on cell survival of endometrial cancer cells, we assessed H2AX phosphorylation, a sensitive marker for double-strand DNA breaks, which can lead to apoptotic cell death." (PMID 38279277, 2024). "As exposure to both DXR and CDDP increased the expression of p-H2AX in immunoblotting, it is assumed that these drugs induced DNA damage to endometrial cancer cells." (PMID 31805725, 2019).
Ewing sarcoma (4 papers, 2015 to 2018). A small round cell tumor that lacks morphologic, immunohistochemical, and electron microscopic evidence of neuroectodermal differentiation. "Given the observed transcriptomic changes of upregulated DNA-damage response, but downregulated DNA-repair, we examined the effects of JIB-04 upon DNA damage in Ewing Sarcoma cells, by quantifying levels of DNA damage-associated phospho-H2AX." (PMID 30237855, 2018). "The combination of CHK1 siRNA and gemcitabine significantly reduced the growth of Ewing sarcoma cells and caused phosphorylation of H2AX." (PMID 29152060, 2017). "The findings on comet assay and γ-H2AX expression suggest that BO-1055 induces far less DNA double strand breaks in hMSC and CD34+ hematopoietic cells when compared to A673 Ewing sarcoma cells." (PMID 27248664, 2016).
gastrointestinal stromal tumor (4 papers, 2008 to 2024). "The treatment of gastrointestinal stromal tumors with imatinib, a widely used selective small-molecule protein kinase inhibitor, results in an upregulation of soluble H2AX." (PMID 38502354, 2024). "In GIST, histone H2AX is a direct mediator of gastrointestinal stromal tumour cell apoptosis upon treatment with imatinib mesylate." (PMID 30060750, 2018). "We have recently shown that histone H2AX also has non-nucleosomal functions, specifically, pro-apoptotic activities in gastrointestinal stromal tumor (GIST) cells treated with the small molecule protein kinase inhibitor imatinib mesylate (Gleevec)." (PMID 18616816, 2008).
heart failure (4 papers, 2018 to 2022). Inability of the heart to pump blood at an adequate rate to meet tissue metabolic requirements. "Protein expression of brain natriuretic peptide (BNP), a biomarker for heart failure, showed an identical pattern to γ-H2AX among the five groups." (PMID 30416645, 2018). "Furthermore, pressure overload-induced heart failure was associated with reduced α4 protein expression, increased ATM/ATR protein kinase activity, increased H2AX expression and Ser139 phosphorylation." (PMID 33737606, 2021). "End-stage heart failure induced by pressure overload for 9 weeks was associated with (i) decreased α4 protein expression, (ii) increased activity of ATM/ATR protein kinases and (iii) increased H2AX expression and Ser139 phosphorylation." (PMID 33737606, 2021).
Immunodeficiency (4 papers, 2018 to 2024). Failure of the immune system to protect the body adequately from infection, due to the absence or insufficiency of some component process or substance. "In summary, DDR represented by phosphorylation of H2AX, ATM, and CHK2 is a highly sensitive tool to identify patients with AT that can be readily distinguished from patients with other combined immunodeficiencies." (PMID 34716846, 2022).
Obesity (4 papers, 2023 to 2025). Accumulation of substantial excess body fat. "Reduced total H2AX, a DNA damage sensor, is also reduced by obesity further indicating that DNA repair could be impaired by obesity." (PMID 38625059, 2024). "The phosphorylation levels of ATM and ATR, as well as those of their recognized downstream effectors, histone H2AX and KAP1, were significantly higher in the VAT biopsies of subjects affected by obesity compared to NW individuals." (PMID 39256343, 2024). "However, there was a tendency towards elevated levels of phosphorylated ATM (pATM), ATR (pATR), H2AX (γ-H2AX) and KAP1 (pKAP1) in subjects with obesity." (PMID 39256343, 2024). "Reduced total H2AX due to DMBA exposure in the lean and by obesity regardless of DMBA exposure raise further concern about the capacity of the obese ovary for DNA repair." (PMID 38625059, 2024).
renal carcinoma (4 papers, 2017 to 2022). A carcinoma arising from the epithelium of the renal parenchyma or the renal pelvis. "Next, we studied how the DNA damage status of sorafenib-induced renal cancer cells is modulated following Nrf2 silencing by analyzing the expression of γ–H2AX." (PMID 30647407, 2019). "After MLN4924 treatment, there was an marked increase in γ-H2AX levels in renal cancer cell lines, compared with DMSO control." (PMID 28717191, 2017). "NNMT overexpression reduced DNA damage in stressed ACHN, 786-O, and 769-P cells as evidenced by the levels of γ-H2AX detected using immunofluorescence staining and western blotting and by DNA damage detection using the comet assay, in cultured renal cancer cell lines." (PMID 35440542, 2022).
retinoblastoma (4 papers, 2013 to 2019). A malignant tumor that originates in the nuclear layer of the retina. "In addition to these, the present differential phosphoproteomic atlas should enable future molecular diagnostic opportunities such as monitoring gamma-H2AX for disease progression after careful analysis of its role in retinoblastoma." (PMID 29914080, 2018). "While CD47 has not been directly linked to DNA repair pathways, its ligand TSP1 is reported to induce γ-H2AX in retinoblastoma." (PMID 31597291, 2019). "In particular, Ser140 of H2AFX also known as gamma-H2AX was found to be hyperphosphorylated in retinoblastoma, which indicated the activation of DNA damage response pathways." (PMID 29914080, 2018). "Next, we analyzed the resolution of dsDNA breaks (γ-H2AX and TP53BP1 foci) in human and mouse retinoblastoma cells following exposure to 5 Gy IR." (PMID 23765217, 2013). "To complement the comet assays, we analyzed the focal accumulation and resolution of proteins that target dsDNA breaks (γ-H2AX and TP53BP1) in human and mouse retinoblastoma cells." (PMID 23765217, 2013).
squamous cell carcinoma (4 papers, 2012 to 2023). A carcinoma arising from squamous epithelial cells. "In addition, when added to culture, vitamin D protected immortalized human keratinocytes and squamous cell carcinoma cells against IR, as shown by a reduction of γ-H2AX foci/cell." (PMID 23029205, 2012).
acute kidney injury (3 papers, 2021 to 2023). Sudden and sustained deterioration of the kidney function characterized by decreased glomerular filtration rate, increased serum creatinine or oliguria. "According to our knowledge, this is the first study that evaluates the immunohistochemical patterns of histone H2AX variants’ expression in an experimental model of ischemia–reperfusion-induced acute kidney injury." (PMID 37175793, 2023). "According to our knowledge, this is the first study that evaluates the immunohistochemical expression of H2AX variants in an experimental model of induced postischemic acute kidney injury, which could be the advantage of this study." (PMID 37175793, 2023). "The decline in PARP1 expression by nicotinamide could suppress cisplatin-induced apoptosis in renal proximal tubular cells as well as acute kidney injury in mice, which might involve the diminished induction of γ-H2AX, a reflection of DNA damage response." (PMID 37773127, 2023). "Considering all that was said above, the aim of this study was to evaluate the immunohistochemical pattern of histone H2A variant (H2AX, γH2AX, H2AXY142ph and H2AZ) expression in an experimental model of ischemia–reperfusion-induced acute kidney injury in spontaneously hypertensive rats (SHRs)." (PMID 37175793, 2023).
esophageal cancer (3 papers, 2013 to 2021). A primary or metastatic malignant neoplasm involving the esophagus. "Artesunate can aggravate DNA damage of esophageal cancer cells and prolong the formation of γ-H2AX foci induced by irradiation." (PMID 32586310, 2020). "Furthermore, it has been recently reported that short term treatment with Imetelstat increases irradiation-induced γ-H2AX and DNA damage in esophageal cancer cells." (PMID 23922990, 2013).
Hyperglycemia (3 papers, 2021 to 2025). An increased concentration of glucose in the blood. "Compared to the control cells, in hyperglycemic conditions, γ-H2AX expression increased significantly, suggesting the role of hyperglycemia in the induction of DNA lesions." (PMID 34961280, 2021). "These two extracts proved a significant antioxidant activity, inhibited the γ-H2AX formation, and improved the expression of HIF1-α, suggesting their protective role on endothelial cells exposed to hyperglycemia." (PMID 34961280, 2021). "The polyphenolic-enriched extracts proved a significant reduction of oxidative stress and γ-H2AX formation and improved the expression of HIF-1α, suggesting their protective role on endothelial cells in hyperglycemia." (PMID 34961280, 2021). "Their effects on hyperglycemia were evaluated by the quantification of oxidative stress and NF-ĸB, pNF-ĸB, HIF-1α, and γ-H2AX expressions." (PMID 34961280, 2021).